CD44 (CD44 molecule (IN blood group))
Diseases named in the same sentence as CD44 in open-access papers (continued):
Sharing a sentence is not in itself a finding about the gene and the disease.
tumor (continued). "Flow cytometry and immunofluorescence assays revealed reduced expression of CRC-SC markers, such as CD44, EpCAM, and CD133, in tumor mass samples explanted from EM127-treated mice." (PMID 40588481, 2025). "The cell-type-specific (defined based on marker gene expression profiles and clustering analysis) expression of CD44, FGF2, FGF10, KDM6A, FN1, and MMP2 in the tumor microenvironment of UCEC was analyzed using the TISCH2 database." (PMID 39833941, 2025). "In contrast, with high Lhpp expression, Cd44 expression significantly decreased, and CD8 + T cell infiltration into the tumor was significantly enhanced." (PMID 40240758, 2025). "The BC-DOX-NPs synergized with the gp60, CD44, and SPARC receptors on tumor cells, resulting in enhanced transcytosis and improved accumulation and uptake inside tumor tissues." (PMID 41304956, 2025). "Given the importance of memory T cells for sustained anti-tumor immunity, we next assessed the effect of LTN on the differentiation of CAR-T cells into a central memory (Tcm, CD44+CD62L+) phenotype." (PMID 40755764, 2025). "CD44-mediated activation of signaling pathways such as Wnt/β-catenin and PI3K/AKT further promote tumor survival and MDR, reinforcing CD44s as key therapeutic targets in TC." (PMID 40363706, 2025). "Ligand–receptor interaction mapping revealed that tumor-derived MIF and macrophage-expressed CD74 (with co-receptor CD44) form a signaling axis in ZDHHC9-high tumors." (PMID 40740766, 2025). "NIR-PIT targeting CD44 induces ICD and increases tumor-infiltrating CD8+ cell counts in syngeneic models of colorectal, lung, head and neck, and oral cancers." (PMID 41011286, 2025). "Some findings also suggest their impact on epithelial markers such as CD44 and ALDH1, with possible effects on stemness and tumor microenvironmental dynamics." (PMID 41368437, 2025). "Repeated exposure of OSCC cells to P.g. slowed proliferation, conferred chemoresistance, enhanced stemness (CD44/CD133 upregulation), and increased tumor sphere formation." (PMID 40924302, 2025). "Regarding tumor cells, the SPP1/CD44 axis is crucial for communication between tumor cells and TAMs." (PMID 41391064, 2025). "Of particular interest are PLGA NPs equipped with ligands like EpCAM, CD44, and CXCR4—that guide therapies directly to tumor sites, improving both selectivity and uptake by cancer cells." (PMID 41233827, 2025). "Our tracking of MSC marker expression revealed progressive CD34 upregulation alongside declining ALCAM, CD44, and ICAM1 levels, indicating complex transcriptional reprogramming during MSC-to-tumor cell transitions." (PMID 40959090, 2025). "In the mIHC, the CCA, marked by CK19, EPCAM and CD44 was observed, further indicating an increase in the CCA and heightened tumor malignancy in DEN + MSCs group." (PMID 39674501, 2025). "Many molecules have been proposed as markers (ALDH1a1, ABCG2, CD44, CD133, CD271, NANOG), but they are also found in non-tumor stem cells and normal melanocytes." (PMID 40806546, 2025). "Specifically, endothelial cell-derived SELE-CD44 signaling may promote the migration and invasion of keratinocytes, which was consistent with previous studies that CD44 (a hyaluronan receptor) enhances tumor cell metastasis through activating PI3K/AKT pathway (Zöller, 2011)." (PMID 41180476, 2025). "CD44 has been recognized as a predictive biomarker for immunotherapy efficacy in CRC and has a role in modulating macrophage polarization and tumor advancement." (PMID 40842994, 2025). "HA-based systems effectively targeted CD44, overexpressing CRC phenotypes, key drivers of stemness and metastasis, showing enhanced tumor accumulation, reduced migration, and selective cytotoxicity compared with free apigenin." (PMID 41440901, 2025). "Investigation of the poor prognosis subtype 6 tissues revealed expression of CD44 and EGFR in ER+ tumor cells." (PMID 39808504, 2025).
tumor (continued). "CD44+/CD24-/low mammospheres are the main component of residual cells after docetaxel treatment and can lead to tumor recurrence in breast cancer." (PMID 39919692, 2025). "The results of this correlation study were confirmed by our results, which showed that CSCs defined by ALDH activity and CD44 expression generate solid, more aggressive ACC tumors while control cells generated a cribriform/tubular, more differentiated tumor." (PMID 40371051, 2025). "HA@CD36i‐TR@siSCD1 can first accumulate at tumor sites by targeting CD44 and then depolymerize in response to the acidic TME and HAase and release CD36i to regulate the tumor microenvironment and lipid uptake." (PMID 39736148, 2025). "The over-expression of CD44-ECD induced by CRAd-synNotch and ADX730 was clearly observed in immunohistochemical studies, and CRAd-synNotch exhibited greater anti-tumor efficacy compared to PBS and CRAd-GFP groups in the T24 mouse model." (PMID 40011711, 2025). "Due to the frequent overexpression of CD44 in OSCC, particularly in tumor-initiating cells, HA-functionalized polymeric nanoparticles offer a promising platform." (PMID 40837711, 2025). "A significant interaction between SPP1 in cluster 1 and CD44 in cluster 4 was observed, consistent with the high SPP1 and CD44 expression at the tumor boundary." (PMID 39862439, 2025). "Our results showed an increase in CD-44 positive staining in Nuak2-OE tumors compared to control tumor-bearing mice, while Nuak2-CR tumors had significantly fewer Ki67, PCNA, and CD-44 positive cells." (PMID 40770117, 2025). "BCSCs are characterized by a more dormant/quiescent mesenchymal-like state and CD44+CD24−/low expression, which are placed at the tumor edge and form micro-metastases at distant sites." (PMID 40676293, 2025). "RNA levels and protein activity of CD44, TNF Receptor Superfamily Member 1A (TNFRSF1A), and ANXA1 were elevated in these high NRF2 tumor cells." (PMID 40583858, 2025). "Conversely, mesenchymal breast CSCs consist mainly of CD44+CD24− cells, are distributed at the tumor periphery, are in a state of static proliferation, and demonstrate strong invasive capabilities." (PMID 40687439, 2025). "Upon binding to (CD74+CD44) complexes, extracellular MIF triggers downstream signaling that exacerbates inflammation, tumor growth, and metastasis." (PMID 40948800, 2025). "FVTF significantly reduced the ability of tumorsphere and soft agar colony formation, the levels of CD44 protein and BMI1, OCT4 and SOX2 mRNAs in HCC cells, and in vivo tumor initiation ability of HCC cells." (PMID 40050970, 2025). "The P-value was 0.04, indicating a statistically significant correlation between CD44 expression and HER2/neu status of the tumor." (PMID 40881916, 2025). "Prior research has indicated that nuclear CD44/acetylated-STAT3 complexes enhance the outgrowth of cells into structures resembling CSCs, promoting tumor formation." (PMID 40083697, 2025). "Our study provides insights into the demographic and clinicopathological landscape of HCC and highlights the elevated expression of CD44, CD90, CD133, and EpCAM in tumor tissues." (PMID 40791212, 2025). "We found that the signaling of VEGFA-VEGFR1, VEGFA-VEGFR2, MIF-(CD74 + CXCR4) and MIF-(CD74 + CD44) was significantly increased in the high-risk state; whereas the signaling of LGALS9-CD45, LGALS9-CD44, and IL1B-IL1R2 was decreased, which may affect the tumor cell adhesion and migration." (PMID 40563096, 2025). "CD44, CD133, and ALDH1A1 are widely used as stem cell markers and play critical roles in promoting tumor growth, invasion, and recurrence." (PMID 40240323, 2025). "Tumor cell motility and invasion, ALDH+ and CD44+/CD24−/low subsets, and mammary CSC self-renewal were decreased by hydroxytyrosol treatment." (PMID 40687439, 2025). "The DNM exhibited targeted binding to CD44-overexpressing SCLC cells, facilitating the precise delivery of the loaded CDDP to the tumor cells." (PMID 41377018, 2025).
tumor (continued). "The stemness genes highly expressed in the C0 subtype included CTNNB1, CD44, and KDM5B, while in the Normal tissue adjacent to neoplasm group, CTNNB1, CD44, and MYC were highly expressed." (PMID 40616092, 2025). "Overall, the 3D antitumorevaluation showed that, after the CD44-targetingpeptide modification, AKPC-siYT was more effective in inducing apoptosisand inhibiting tumor spheroid growth than MC3-siYT." (PMID 40176316, 2025). "Next, accordingly to the strong inhibition of tumor growth, a significant reduction in phosphorylated ERK 1/2 and Akt – key signaling molecules downstream of CD44 – was observed in the tumors of mice treated with sTN58." (PMID 40342488, 2025). "To this end, we knocked down CD44 in both human BrCa cell lines (MCF-7 and T-47D) and primary tumor cells isolated from MMTV-PyMT spontaneous BrCa mouse model." (PMID 40409554, 2025). "Focused on this cluster number “3”, cells from the three samples were found to express some epithelial/tumor markers at distinct levels, with markers including EPCAM, CD44, KRT8, ITGA6, and CLDN4." (PMID 41440935, 2025). "Four phenotypes characterized by expression of CD44 and CD133 (ALDH1/CD44/CD133, CD44, CD44/SOX9 and CD44/CD133) were more prevalent in grade 1 tumor biopsies." (PMID 39888143, 2025). "To elucidate the mechanisms by which TZ‐dSA3‐12 prevents tumor recurrence, we examined the populations of memory T cells in splenocytes, specifically effector memory T cells (Tem, CD3+CD8+CD44+CD62L−) and central memory T cells (Tcm, CD3+CD8+CD44+CD62L+)." (PMID 40492586, 2025). "Remarkably, adv treatment significantly induced the infiltration of central memory CD8+ T cells (CD44+ CD62L+) into the tumor microenvironment and spleen, as well as effector memory CD8+ T cells (CD44+ CD62L−) in the spleen." (PMID 41045932, 2025). "CAF-derived HA contributes to metastatic tumor growth mediated by YAP, likely through the CD44/FAK axis." (PMID 39946200, 2025). "Conversely, in CD44-positive JIMT-1 models, CAR NK cells exhibited reduced efficacy, struggling to penetrate the ECM and reach tumor antigens effectively." (PMID 40075578, 2025). "It is well known that both CD44 and HIF contribute to cancer stemness in the tumor microenvironment." (PMID 40011711, 2025). "CD44-expressing HNSCC cells have a greater propensity for metastasis and inhibit the tumour killing effect of cytotoxic T lymphocytes (CTLs) by downregulating the Fas-FasL pathway." (PMID 40181975, 2025). "AGD1 mediates the stemness and apoptosis of PCSCs and promotes docetaxel treatment resistance by enhancing tumor growth and metastasis through USP10/METTL13-mediated CD44 mRNA decay in CRPC." (PMID 39806412, 2025). "Flow cytometry analysis revealed significant increases in CD80+CD86+ DCs, CD8+CD3+ T cells, and CD44+CD62L‐TEM cells, indicating that FABP5 inhibition effectively enhanced immune responses in the tumor microenvironment." (PMID 40956367, 2025). "WB assays also confirmed that treatment with rhSFRP1, rmSFRP1, and CM from CAF-Sfrp1 enhanced tumor stemness and EMT activity, as evidenced by upregulation of CD44, CD133, ZEB1, Vimentin, and N-cadherin, along with the downregulation of E-cadherin." (PMID 40225580, 2025). "In tumor-promoting settings, SPP1 interacts with its receptors—primarily integrins and CD44—to activate multiple downstream signaling cascades that facilitate cancer cell migration, invasion, and metastatic spread." (PMID 41391064, 2025). "In one study, CD44-/CD105- cells were injected subcutaneously into NOD SCID mice and tumor growth was monitored by MRI and PET/CT." (PMID 40642092, 2025). "The labeling of tumor cells can be achieved by utilizing HCC stem cell markers, including CD133, CD326, CD90, CD44, and CD338, as reported in the previous literature." (PMID 39940889, 2025). "Tumor cells were also significantly more localized within CD74 MIF and MIF CD44 neighborhoods, reinforcing the role of these regions as hubs of immune suppression." (PMID 40364843, 2025).
tumor (continued). "However, in GSCs, whether CD44 variant isoforms have the same activity as observed in mouse tumor cells or what variant isoforms of CD44 participate in such functions of xCT are not known." (PMID 40002787, 2025). "A further study reported upregulation in PD-L1 levels in CD133+CD44+ colorectal (CRC) cells and even higher in CD133+ CD44+ colorectal CSCs and CSC-enriched tumor spheres." (PMID 41233805, 2025). "We then analyzed the immune cell infiltration in the tumor microenvironment (TME) and found that the percentage of tumor-infiltrating effector CD8+ T cells, which express IFN-γ, GzmB, and CD44, was elevated in L-SeMet-treated mice." (PMID 40141154, 2025). "In the same CT26 tumor model, one-week of CBL0137 treatment increased the number of infiltrating CD44+CD8+ effector T cells." (PMID 39706891, 2025). "For example, at the same cut-off value of ≥5% of tumour cells with positive immunostaining, the expression of wtEGFR was accompanied by co-expression with HER2 (35%), HER4 (30%), EGFRvIII, CD44 (44%), CD109 (4%), and HER2/HER4 (29%), respectively." (PMID 40227788, 2025). "As a result of the interaction of hyaluronic acid with CD44, EGFR-mediated pathways are activated, leading to tumor cell growth, tumor cell migration, and chemotherapy resistance in solid cancers." (PMID 40558504, 2025). "Cross-targeting strategies are also promising; CD44-directed therapies, for instance, induce apoptosis in CD90+ cells and hinder tumor formation." (PMID 41438763, 2025). "A recently developed method for tumor cell targeting is therapy with chimeric antigen receptor (CAR) T cells, successfully applied for CD44+ tumor cell elimination." (PMID 40114966, 2025). "CD44 knockdown reduced FGFR2 expression and impaired tumor formation, and the reverse was also observed, as FGFR2 knockdown reduced CD44 levels and stem cell markers, paradoxically increasing c-Myc and SOX-2." (PMID 41303727, 2025). "Research has also shown that CD44-targeted CAR-NK cells retain cytotoxicity when combined with cisplatin, with this combination showing greater anti-tumor efficacy than sequential treatments." (PMID 41425568, 2025). "Its interactions with binding proteins—such as CD44, EGFR, integrins, CD280, and CD176—and its dual role in both tumor and stromal compartments highlight a unique therapeutic vulnerability that extends beyond conventional single-pathway targeting strategies." (PMID 41479915, 2025). "Of note, in Trp2.Combo + a-PD1 treated animals we also observed a significant increase in the activated Ly6c+ CD44+ CD8+ T cells in circulation, which negatively correlated with the tumor volume." (PMID 40216735, 2025). "In the IHC staining of tumor tissue, the CCA-positive area, marked by CK19, CK7, EPCAM, and CD44, in silent IGF2R-MSCs groups were lower than those in the MSCs group." (PMID 39674501, 2025). "Our group has previously reported enrichment of stem cell expression with the markers CD44, HLA-I, pan-CK, and p-EGFR in relapsed HNSCC after induction chemotherapy compared to the primary tumor." (PMID 40738059, 2025). "This promotes CSC formation by upregulating markers such as CD44 and CD133, especially under hypoxic conditions within the tumor microenvironment." (PMID 41010517, 2025). "In particular, Wi-N and TEG caused a stronger reduction in the self-renewal capability of CSCs than Wi-A, as evidenced by a tumor spheroid formation assay and analyses of stemness-related genes (ALDH1, CD44, NANOG, CD133, SOX2)." (PMID 39859209, 2025). "PD‐L1 is closely related to the expression of stem cell marker genes CD44 and LGR5 in ovarian cancer and is involved in tumour recurrence." (PMID 40665579, 2025). "PD-1+Tim3+ cells were increased in CD4+CD44+/CD8+CD44+T cells, indicating that the CD4+ and CD8+ T cells with exhaustion phenotype were predominantly present in tumor nodules." (PMID 40777028, 2025).
tumor (continued). "We then sought to understand the relationship between the proteoglycan versican and the receptors CD44 and the EGFR family, which are expressed on the membrane of carcinomatous cells and identified as key mediators linking versican to tumor cells." (PMID 40005948, 2025). "The specificbinding of AKPC to CD44 enabled a high extent of cellularendocytosis of AKPC-siYT, efficiently delivering siRNA into the cellsand inducing potent inhibition of tumor proliferation." (PMID 40176316, 2025). "A moderate or lower level of PD-1 expression in CD44+CD8+ TIL cells facilitated the long-term maintenance of CD8+ TIL cells, thus providing sustained tumor control." (PMID 40236705, 2025). "The DNM exhibits a specific affinity toward CD44-overexpressing tumor cells, enabling the effective delivery of the loaded cisplatin (CDDP) to the tumor cells." (PMID 41377018, 2025). "We found that two representative molecules involved in EMT, CD44 and HIF1A, were expressed at high levels in IBC tumour cells." (PMID 40624675, 2025). "In the context of PMNs, CD44 plays a critical role by promoting EMT, increasing cell motility and invasion, and facilitating tumor–stroma interactions." (PMID 41479915, 2025). "Whereas interactions necessary of T‐cell activation, like MIF (interacting with CXCR4, CD74 and CD44), PPIA (interacting with BSG) and CXCL16 (interacting with CXCR6 on CD8+ T‐cells) were down‐regulated in high EGFR expressing tumour cells." (PMID 40621643, 2025). "Network and pathway enrichment analyses highlighted suppression of CD44-centred signalling, epithelial–mesenchymal transition (EMT), and fibrogenesis-related genes, indicating impaired tumour plasticity and reduced metastatic potential." (PMID 41516237, 2025). "Fluorescence imaging showed that 5FU increased both CD44 and CD133 expressing cells in the tumor tissues of 5FU treated mice suggesting that this chemotherapeutic drug encourages CSC enrichment." (PMID 40045186, 2025). "CD44 variations could serve as more reliable biomarkers for advanced or chemo-resistant TC compared to conventional markers like thyroglobulin, as they reflect the tumor’s ability to evade apoptosis, maintain stem-like features, and efflux drugs, factors central to MDR." (PMID 40363706, 2025). "Previous studies have shown that when CD74 and CD44 are both present in CRC, the tumor becomes more aggressive." (PMID 40842994, 2025). "By binding to receptors such as CD44 and integrins, SPP1 activates key signaling pathways including PI3K/AKT/mTOR, Slug/Snail, MAPK/NF-κB, and Ras/Raf/ERK, thereby promoting tumor cell proliferation, migration, invasion, adhesion, and EMT." (PMID 41384115, 2025). "Analysis of TCGA-LUAD data revealed that elevated IGF2BP3 expression correlates with advanced tumor stages and poor patient survival, consistent with its established role in stabilizing pro-survival transcripts such as c-MYC and CD44." (PMID 40313617, 2025). "MicroRNAs, including miR-34a and the miR-200 family, also modulate CD44 expression by targeting its mRNA, influencing processes such as epithelial-mesenchymal transition (EMT) and tumor growth." (PMID 40363706, 2025). "The reduction in CD44v6 was accompanied by decreased levels of CD44, CD24, and CD133, which are widely recognized as key CSC markers involved in regulating self-renewal, differentiation potential, and tumor aggressiveness (p < 0.001)." (PMID 40069421, 2025). "In tumor resection specimens of EC patients, the overall percentages of FAK+, CD44+, HIF-1α+, and Ki67+ cells were higher in tumor nests than in the tumor stroma, with Ki67+ cells reaching statistical significance (p < 0.001)." (PMID 38727811, 2024). "We validated that IGF-1 enhanced the proliferative ability of tumor cells, elevated the protein and mRNA expression of cancer stem cell markers CD133 and CD44, along with enhanced tolerance to cisplatinoid drugs and in vitro sphere formation ability." (PMID 38413558, 2024).